CZIB (CXXC motif containing zinc binding protein)
Synonyms: C1orf123; FLJ20580
Tractability: PROTAC: ubiquitination databases record sites on it.
Gene: Protein-coding gene on chromosome 1 (53,214,099 to 53,220,652, reverse strand). Ensembl gene ENSG00000162384.
Subcellular location (Human Protein Atlas): Cytosol; Mitotic spindle; Vesicles
Gene Ontology:
Molecular function: protein binding; zinc ion binding
Genetic constraint (gnomAD): Loss-of-function variants: 26 observed, 29 expected, observed/expected ratio (o/e) 0.9, 90% interval 0.66 to 1.24. The upper end of that interval is the gene's LOEUF score, 1.24, which puts it in group 5 of 6, group 1 being the genes least tolerant of losing a copy. Missense variants: 179 observed, 207.24 expected, observed/expected ratio (o/e) 0.86, 90% interval 0.76 to 0.98. Synonymous variants: 78 observed, 74.94 expected, observed/expected ratio (o/e) 1.04, 90% interval 0.87 to 1.26.
Homologues: Orthologues: chimpanzee CZIB (100% identical), macaque CZIB (98% identical), guinea pig CZIB (96% identical), pig CZIB (96% identical), mouse Czib (95% identical), rabbit CZIB (95% identical), rat Czib (94% identical), dog CZIB (94% identical), zebrafish czib (82% identical), tropical clawed frog czib (81% identical), Caenorhabditis elegans F46B6.12 (48% identical), Drosophila melanogaster CG4646 (46% identical).
Diseases named in the same sentence as CZIB in open-access papers:
CZIB is named in the same sentence as 4 diseases in open-access papers, as found by Europe PMC text mining. Sharing a sentence is not in itself a finding about the gene and the disease.
CZIB shares sentences with these, for which no sentence is quoted: cancer (1 paper); multiple myeloma (1); osteoporosis (1); Polycystic Ovarian Syndrome (1).